TNF (tumor necrosis factor)
Diseases named in the same sentence as TNF in open-access papers (continued):
Sharing a sentence is not in itself a finding about the gene and the disease.
psoriasis (continued). "Glycyrrhizic acid compound ointment significantly improved imiquimod-induced psoriasis in mice and reduced the secretion of TNF-α, IL-12, IL-17, and IL-23 in mouse skin, and showed a stronger therapeutic effect than calcipotriol ointment." (PMID 37643205, 2023). "Another study also reported that the maintenance of psoriasis skin inflammation mainly depends on the recruitment and activation of macrophage and the release of TNF-α." (PMID 37117184, 2023). "Regarding PCR results; a significant increase in lncRNA NEAT, VEGF and TNF-α genes expression in psoriasis patients as compared to healthy control subjects (p value < 0.001)." (PMID 37531036, 2023). "Among patients who received biologic DMARDs, 8 psoriasis patients and 1 PsA patient received IL-17 blockers, one PsA patient was treated with an IL-23 inhibitor, and another received a TNF-inhibitor." (PMID 37662940, 2023). "The immunologic pathogenesis of psoriasis involves the continuous action of TNF‐α, IL‐23, and IL‐17A from upstream to form the skin rash." (PMID 37305885, 2023). "The cytokines driven by NF-κB activation in psoriasis, including IL-17, TNF-α, IL-1β, and IL-6, were increased by IMQ exposure (p < 0.05)." (PMID 37111171, 2023). "On the other hand, TNF-α, IL-23, IL-17 and IL-22 were reported to be fundamental in the pathogenesis of psoriasis." (PMID 37763769, 2023). "The same feed-forward stimuli are observed in psoriasis, where TNF-α, IL-26, and IL-29 are induced by IL-17, resulting in maintaining barrier dysfunction and dysregulation." (PMID 38139369, 2023). "TNF-α is a key agent in inflammatory disorders, including psoriasis and contact dermatitis, and mediates apoptosis, inflammation, and tumorigenesis." (PMID 38102220, 2023). "Th1 cells can increase macrophages and cytotoxic T cells - mediated immune response by releasing interferon-γ (IFN-γ) and TNF-α, which are critical players in the development of psoriasis." (PMID 37942312, 2023). "Many IMIDs cluster around signature cytokines including interleukin (IL)-23 in IBD and psoriasis, IL-6 in RA, and tumor necrosis factor-α (TNFα) as a common downstream effector in inflammatory arthritis and IBD." (PMID 36377205, 2023). "TNF-α inhibitors, the oldest biologics used to treat psoriasis, have been demonstrated to play an important role in different types of psoriasis." (PMID 38008779, 2023). "For psoriasis, these TNF-a inhibitors can be used alone or with methotrexate to decrease the frequency of antidrug antibodies (ADAs)." (PMID 37942312, 2023). "After 6–8 weeks of administration, this probiotic strain reduces plasma CRP levels in all three conditions, reduces TNFα in chronic fatigue syndrome and psoriasis, and reduces IL-6 in UC and chronic fatigue syndrome." (PMID 38055306, 2023). "Different studies in humans refer that anti TNF-α agents increase Tregs and decrease the Th17 cells frequency in peripheral blood of psoriasis patients." (PMID 36901778, 2023). "T cell activation, which associated with the secretion of proinflammatory cytokines drive the psoriasis, including interleukin (IL)-17A, tumor necrosis factor-α(TNF-α), interferon IFN-γ and IL-22." (PMID 37029373, 2023). "The activation of IL-12 signaling in keratinocytes alleviates psoriasiform skin inflammation, whereas IL-12 activates Th1 cells to produce INF-γ and TNF-α, which act as surrogates for psoriasis by driving skin inflammation." (PMID 37762693, 2023). "Infliximab was the most common TNF-α inhibitor used and resulted in cases of paradoxical psoriasis, totaling 62.3% of the cases reported." (PMID 37664349, 2023). "Plaque-type psoriasis is characterized by the tumor necrosis factor-alpha (TNF-α)-IL-23-Th17 inflammatory pathway." (PMID 38089952, 2023). "They developed NLCs for topical application, incorporating tacrolimus and TNFα-siRNA to treat psoriasis and inhibit the production of TNFα, a proinflammatory cytokine overexpressed in the psoriasis condition." (PMID 36771111, 2023).
psoriasis (continued). "For example, TNF-α is involved in psoriasis inflammation and has been shown to be an independent predictor of hepatic fibrogenesis and disease progression." (PMID 36836776, 2023). "Between January 2010 and September 2022, 165 patients with psoriasis were treated with biologics targeting TNF-α, IL-17, or IL-23." (PMID 36902720, 2023). "Until today, the TNF-α inhibitors have revolutionized the treatment of many other immune-mediated diseases, such as inflammatory bowel disease, ankylosing spondylitis, and psoriasis." (PMID 36814288, 2023). "At baseline, serum levels of effector cytokines (IFN-γ, IL-17 and IL-22) and proinflammatory cytokines (IL-6, TNF-α) were higher in psoriasis patients relative to healthy controls." (PMID 37681925, 2023). "When exposed to multiple triggers such as IMQ, stressed keratinocytes produce inflammatory cytokines, including IL-1β, IL-6, and TNF-α, which contribute to dermal DC activation and the initiation of psoriasis." (PMID 37717073, 2023). "The tumor necrosis factor (TNF)-α/interleukin (IL)-23/IL-17 axis is the mainstay of psoriasis pathogenesis." (PMID 36902720, 2023). "Sequential biopsies obtained from psoriasis patients undergoing treatment with etanercept, a TNF antagonist used for psoriasis therapy, demonstrated a significant reduction in phosphorylated NF-kB/RelA." (PMID 38203337, 2023). "IFX is a chimeric anti-TNF mAb approved for SpA, Crohn’s Disease (CD), psoriasis (Ps), psoriatic arthritis (PsA), RA, and ulcerative colitis (UC)." (PMID 37176711, 2023). "These TNF inhibitors have direct inhibitory effects on TNF-α, which is involved in the inflammatory pathways that contribute to the etiology of psoriasis, hidradenitis suppurativa, and a number of other inflammatory dermatological conditions." (PMID 37304177, 2023). "Adalimumab, an anti-TNF antibody, and secukinumab, an anti-IL-17A antibody, have been approved for psoriasis treatment." (PMID 37377955, 2023). "Pro-inflammatory cytokines and chemokines, including IL-6, IL-8, and TNF-α, play a critical role in the initiation and progression of many chronic inflammatory skin diseases, such as psoriasis or atopic dermatitis." (PMID 36979014, 2023). "It is well known that an increase in the adipose tissue in obesity tends to produce excessive amounts of proinflammatory cytokines which participate in the pathophysiology of psoriasis, including IL-8, IL-6, and TNF." (PMID 37447169, 2023). "These cells secrete tumor necrosis factor α (TNF-α), interleukin-6, and other pro-inflammatory cytokines that mediate the pathogenesis of psoriasis." (PMID 38140019, 2023). "This is in accordance with a former study that showed a correlation between serum levels of IFN-γ, TNFα, IL-18 and IL-12 and psoriasis severity." (PMID 37049538, 2023). "Up to date, four classes of biologics targeting inflammatory cytokines are used to treat psoriasis: TNF-α inhibitors; IL-12/23 inhibitors; IL-17 inhibitors; and IL-23 inhibitors." (PMID 37239484, 2023). "It is known that the IL-23/IL-17 axis is essential in the immunopathogenesis of psoriasis, with TNF-α and IFN-γ being the primary pro-inflammatory signals." (PMID 37305120, 2023). "Numerous pharmacogenetic studies in patients with psoriasis treated with BTs (specifically anti-TNF and UTK) have been conducted in the search for predictive biomarkers of effectiveness and/or toxicity." (PMID 37240048, 2023). "The frequencies of psoriasis reports between the TNF inhibitors ranged from 0.29 to 1.90%: certolizumab pegol 1.90%, adalimumab 1.16%, golimumab 0.69%, infliximab 0.52%, and etanercept 0.29%." (PMID 37369753, 2023). "In psoriasis, activated MCs expressing IL-17, TNF-α, and IL-22 are consistently found enriched in involved and uninvolved skin compared with normal skin." (PMID 36675078, 2023). "Psoriasis is a chronic inflammatory skin disease with enhanced immune axis of tumor necrosis factor (TNF)-α/interleukin (IL)-23/IL-17." (PMID 36769622, 2023).
psoriasis (continued). "These novel biologics, which specifically target molecules such as TNF-α, IL-17, and IL-23, have enabled revolutionary improvements in treating severe psoriasis." (PMID 38203337, 2023). "NB-UVB treatment suppresses serum levels of psoriasis-driving cytokines, such as tumor necrosis factor (TNF)-α, IL-8, IL-12, IL-17, IL-22, IL-23, and IL-34 and elevates the levels of IL-10, an anti-inflammatory cytokine, in patients with psoriasis." (PMID 36928592, 2023). "In terms of safety profile, the incidence of severe adverse events in psoriasis patients receiving TNF-α inhibitors is low." (PMID 37006279, 2023). "In this review, we aim to review the current literature regarding proposed mechanisms of action and published cases of TNF-α inhibitor-induced psoriasis." (PMID 37664349, 2023). "A selective estrogen receptor modulator, raloxifene, was suggested to be potentially effective for the treatment of psoriasis as an inhibitor of IL-12p40 and tumor necrosis factor (TNF)-α." (PMID 37035327, 2023). "The objective of this study was to evaluate the influence of single-nucleotide polymorphisms (SNPs) on the drug survival of tumor necrosis factor inhibitors (anti-TNF) medications and ustekinumab (UTK) in patients diagnosed with moderate-to-severe psoriasis." (PMID 37240048, 2023). "Anti-psoriasis medications, as contributors to thyroid anomalies, include anti-TNF-α drugs; their contributions remain a matter of debate." (PMID 36902323, 2023). "Keratinocytes in psoriatic lesions are potentially rich in LL-37 and can induce the production of TNF-α and IL-6 in dendritic cells, further indicating that neutrophils are involved in worsening psoriasis." (PMID 37964882, 2023). "In contrast, overproduction of type I IFN can induce several diseases and drug side effects, such as psoriasis, lupus, and anti-TNF–induced paradoxical psoriasis." (PMID 36633910, 2023). "Immune targeting therapies of biological antibody for TNF-α, IL-12, IL-17 and IL-23 has revolutionized psoriasis development." (PMID 37492568, 2023). "Their analysis of administrative databases in Tuscany aimed to evaluate the pattern of biologic drug use for psoriasis and revealed a higher persistence to newer biologic drugs compared to anti-TNF drugs (including etanercept and adalimumab)." (PMID 38139989, 2023). "The central role of the TNF-α/IL-23/IL-17 axis in the pathogenesis of psoriasis has been demonstrated in numerous studies." (PMID 38008779, 2023). "We further showed induction of CXCL12 in HMEC-1 cells by either mixture of pro-inflammatory cytokines (IL-17A, IL-22, TNF, IL-1α, and oncostatin M), or serum from active psoriasis patients." (PMID 37736772, 2023). "This exerts control over the genes that can be associated with psoriasis to start inflammatory cytokine secretion (e.g., IFN-γ, TNF-α, IL-2, IL-12, IL-23)." (PMID 38258034, 2023). "Even with the Fc domain fused to the TNFR CRD, TNFα levels are higher in psoriasis patients taking etanercept compared to adalimumab and infliximab." (PMID 37534280, 2023). "A plausible mechanism through which GLP-1 improves psoriasis is by blocking expression of IL-17, IL-22, IL-23 and TNF-α through the IL-23/Th-17 pathway." (PMID 37266425, 2023). "Most of these applications showed effectiveness against skin-associated diseases, such as ItP of IL-10 for atopic dermatitis, STAT3 siRNA for skin cancer, and TNF-α drug etanercept for psoriasis." (PMID 38140019, 2023). "If malignancy is concomitant with psoriasis, TNF-alpha inhibitors should be avoided, while IL-17 inhibitors as well as IL-23 inhibitors are more suitable options." (PMID 37631384, 2023). "Biologics targeting TNF-α, IL-23, and IL-17 have been developed and have shown significant therapeutic effects in psoriasis." (PMID 36902720, 2023). "Currently, there are more than 100 reports of patients who developed psoriasis after beginning treatment with a TNF-α inhibitor for the management of an alternative autoimmune disease." (PMID 37664349, 2023).
psoriasis (continued). "TNF‐α, as well as IL‐1β, induced keratinocyte activation plays a pivotal role in the pathogenesis of many inflammatory skin diseases, such as psoriasis, and different inhibitors of these cytokines have been proven to be a promising treatment in such diseases." (PMID 36544622, 2023). "It is well established from research on human and mouse models that the TNF-α-IL-23-IL-17 axis plays a central role in the pathogenesis of psoriasis." (PMID 36675078, 2023). "Psoriasis patients with comorbidities usually exhibit a more severe inflammatory status driven by IL-17 and TNF-α." (PMID 38029150, 2023). "Anti-IL-17 agents show impressive clinical, histological, and transcriptional resolution of psoriasis, while anti-TNF-α agents can induce paradoxical psoriasis in patients with autoimmune diseases other than psoriasis." (PMID 37717073, 2023). "Since this cytokine show synergy with TNF-α, IL-1α, IL-17A, and IL-22 in production of antimicrobial peptides, it is considered to be involved in pathogenesis of psoriasis." (PMID 37881433, 2023). "A recent network meta-analysis involving 167 studies and 58.912 patients with psoriasis analyzed the efficacy of systemic pharmacological treatments for chronic plaque psoriasis, including anti-TNF-α and cytokine inhibitors." (PMID 37372997, 2023). "Tumor necrosis factor alpha (TNF-α), dendritic cells, and T cells are believed to play roles in the pathogenesis of psoriasis; meanwhile, the detailed molecular pathogenesis of this disease is not thoroughly known." (PMID 37953296, 2023). "In the pathogenesis of both axSpA and psoriasis, deregulation of classic inflammatory cytokines such as interleukin (IL) 1, IL-12/23, IL-17, and IL-23 and tumor necrosis factor alpha (TNFα) are observed." (PMID 37559146, 2023). "HD 1–2 were found to be highly expressed in psoriasis scales and are activated in keratinocytes by TNF- and/or IFN-c." (PMID 36995575, 2023). "TNF-α inhibitors have been used to treat autoimmune disease for many years before they are introduced to psoriasis." (PMID 38029150, 2023). "Recently, biologics (including TNF-α inhibitors, IL-17, and IL-12/23 inhibitors) have become a revolutionary modality in the management of psoriasis based on randomized controlled trial evidence and large sample size real-world research." (PMID 38029150, 2023). "Anti-TNFα and anti-IL-17 are prominent examples for different classes of biologics that are used to treat moderate-to-severe psoriasis and hidradenitis suppurativa." (PMID 37047412, 2023). "Attractively, the FeN4O2-SACs treatment has largely weakened the M5-stimulated psoriasis-like morbidity status and shows inhibited cell proliferation and reduced TNF-α, IL-6, and IL-8 mRNA expressions." (PMID 37880231, 2023). "Testing the CRP and PLR during treatment with TNF-a inhibitors in patients with psoriasis is relevant and useful for monitoring treatment responses to these biologics." (PMID 36769622, 2023). "MiR-146a and MiR-155have been found upregulated in psoriasis, thus promoting TNF expression, and correlating with IL-17 – driven inflammation." (PMID 37484864, 2023). "The activated JNK pathway in keratinocytes can mediate the recruitment of immune cells in psoriasis by regulating the production of inflammatory cytokines/chemokines, such as IL-6, IL-8, IL-23, IFNγ and TNFα, and CCL20 and hβD-2." (PMID 38008779, 2023). "Biologics targeting TNF-α, IL-12/23, and IL-17 are systemic therapies that can dramatically improve the condition of psoriasis." (PMID 36769825, 2023). "For patients with psoriasis and psoriatic arthritis, first-line therapy is represented by TNF-α inhibitors, ixekizumab, secukinumab, guselkumab, and risankizumab." (PMID 37631384, 2023). "It has proven its efficacy in reducing the inflammation in psoriasis by reducing free radicals via different mechanisms such as the suppression of the NF-κB, IL-1β downregulation IL-6, and TNF-α." (PMID 36769305, 2023).
psoriasis (continued). "In this study, we found that the use of IL-17i and IL-23i was a protective factor for psoriasis compared with TNF-αi and was able to maintain stable psoriasis." (PMID 38020100, 2023). "Important cytokines like IL-17, IL-22, IL-23, and TNF-α are involved in the pathogenesis of psoriasis, as well as other crucial transduction pathways like the NF-κB and STAT signaling pathways." (PMID 37828492, 2023). "Imiquimod was observed to induce more severe psoriasis in obese mice, and the levels of IL-6, TNF- α, and Th17 cells, were simultaneously elevated." (PMID 36982669, 2023). "Tumor necrosis factor (TNF) inhibitors such as infliximab, adalimumab, and etanercept have been approved for the management of psoriasis and other inflammatory conditions, and have extensively discussed guidelines for such therapies." (PMID 37371141, 2023). "A total of 206 patients diagnosed with moderate-to-severe psoriasis who had been under treatment with anti-TNF or anti-IL12/23 (UTK) agents for at least 4 months were included in this study." (PMID 37240048, 2023). "Out of the TNF inhibitors studied, certolizumab pegol exhibited the highest reported frequency of psoriasis." (PMID 37369753, 2023). "The therapeutic targets for psoriasis are diverse and include the utilization of anti-tumor necrosis factor-alpha (TNF-α) antibodies, anti-interleukin (IL)-12/23p40 antibodies, and anti-IL-17 antibodies." (PMID 37928519, 2023). "Targeted anti-psoriasis therapies namely biological agents have been developed with the recognition of TNF-a, IL-23/Th17 axis and IL-22/Th22 pathway, representing better efficacy as well as relative safety." (PMID 37942312, 2023). "Proinflammatory M1 macrophages contribute to psoriasis development, especially during the early phase, by producing TNF-α." (PMID 37507888, 2023). "In terms of bDMARDs in psoriasis treatment, they are usually divided into targeting cells (T-cells or antigen-presenting cells) and cytokines (for example, TNF (tumor necrosis factor), IL-12, IL-17, IL-23)." (PMID 37298045, 2023). "In this study, the concentrations of IL-6, IFN-γ, and TNF-α were significantly elevated in the psoriasis group compared with the healthy group." (PMID 37596509, 2023). "Both IL-17 and TNF cytokines have been demonstrated to play pivotal roles, and their antagonists are effective treatments for psoriasis." (PMID 37492568, 2023). "Additional biological drugs, including infliximab, adalimumab, certolizumab, and etanercept, selectively interact with tumor necrosis factor-alpha (TNF-alpha), a molecule that is implicated in the immune response associated with psoriasis." (PMID 38222196, 2023). "The TNF-α inhibitor etanercept was effective in treatment-resistant depression and reduced depression and anxiety in psoriasis patients." (PMID 37583842, 2023). "Numerous pharmacogenetic studies have researched the impact of genetic biomarkers on psoriasis disease response, especially to treatment with TNF-α inhibitors." (PMID 37631238, 2023). "Adalimumab is a biologic medication used to treat inflammatory skin conditions such as Psoriasis and Hidradenitis suppurativa (HS), which targets TNF-α." (PMID 37250640, 2023). "This review focuses on cases of paradoxical psoriasis provoked by anti-TNF-α drug usage currently published in the literature." (PMID 37664349, 2023). "There is ample evidence that the skin inflammation exhibited by psoriasis is caused by inflammatory mediators such as TNF-α, that macrophages are a key source of TNF-α and that S1P has a significant effect on this process by activating S1PR1 on macrophages." (PMID 37072847, 2023). "The small number of psoriasis reports in the methotrexate-treated patient cases allowed for overlapping 95% CIs between the individual TNF inhibitors." (PMID 37369753, 2023).